WEE1 (WEE1 G2 checkpoint kinase)
Diseases named in the same sentence as WEE1 in open-access papers (continued):
Sharing a sentence is not in itself a finding about the gene and the disease.
breast cancer (continued). "The mutational and mRNA expression status of PIK3CA, PIK3R1 and AKT1, and expression status of other genes involved in the PI3K pathway (EGFR, PDK1, PTEN, AKT2, AKT3, GOLPH3, WEE1, P70S6K) were assessed in a series of 458 breast cancer samples." (PMID 24229379, 2013). "Different mechanism of action for MLN4924 radiosensitization (p21 in breast cancer cells vs. CDT1 and WEE1 in pancreatic cancer cells) reflected a cell-line dependent response to inactivation of SCF E3 ligases." (PMID 22457814, 2012). "In a preclinical study on breast cancer cells with acquired CDK4/6 inhibitor (CDK4/6i) resistance, authors discovered a collateral sensitivity towards the Wee-1 inhibitor adavosertib, which specifically depleted only CDK4/6i-resistant but not CDK4/6i-sensitive cells in a co-culture setting." (PMID 39915607, 2025). "When WEE1 is targeted, it inhibits the growth of CDK4/6i-resistant breast cancer cells." (PMID 37475713, 2023). "A study of breast cancer demonstrated that ZFP36 could inhibit c-Jun expression, which resulted in the increase of Wee1 expression and prevented cell cycle progression from the S into the G2 phase." (PMID 36685851, 2022). "Interestingly, combined Wee1 and ATR inhibition was as toxic to cancer stem cells as to bulk breast cancer cells, potentially explaining the antimetastatic effect of the combination treatment." (PMID 35251998, 2022). "The clinical relevance of WEE1 expression in breast cancer has been little studied and to our knowledge has never been assessed in large series of TNBC." (PMID 34227743, 2021). "SLFN11 protein associated with both preclinical and patient treatment response to DDA, but not to non-DDA or DDRi therapies, such as WEE1 inhibitor or olaparib in breast cancer." (PMID 33339894, 2021). "Earlier studies on WEE1 inhibitors as monotherapies in breast cancer showed limited activities due to a lack of a clear understanding of the mechanisms responsible for their effects on cell cycle distribution." (PMID 32555285, 2020). "The combined effect of Herceptin and FKA on downregulation of Cdc2 inhibitors (i.e., Myt1 and Wee1) and inhibitors of apoptosis (i.e., survivin and XIAP) is likely attributable to the enhanced growth inhibition of HER2-overexpressing breast cancer cells by these two agents." (PMID 28335434, 2017). "As opposed to our results, a low expression of Wee1 has been described in different studies of breast cancer and melanomas, as well as in non-small-cell lung cancer." (PMID 23767999, 2013). "Our studies in breast cancer showed that breast cancer stem cells were less sensitive to AZD1775 compared to bulk cancer cells, which could be due to reduced drug uptake or decreased reliance on Wee1 signaling." (PMID 35251998, 2022). "Therefore, AZD1775 is effective as a single agent in ER+ breast cancer cells that are resistant to antiestrogen and CDK4/6 inhibitors but the anti-proliferative effect of WEE1 inhibition in these cells is hampered when combined with antiestrogens or CDK4/6 inhibitors." (PMID 34277427, 2021). "Whether low WEE1 expression is associated with increased cyclin E-CDK2 activity and elevated intrinsic RS, and consequently increased AZD1775 sensitivity in these breast cancer cell lines is not known." (PMID 32628111, 2020). "Interestingly, knockdown of Wee1 by siRNA has been found to reduce viability of breast cancer cells but not of normal mammary epithelial cells." (PMID 24223931, 2013).
breast cancer (continued). "Unlike the mechanism by which MLN4924 sensitized pancreatic cancer cells to radiation via causing accumulation of CDT1 and WEE1 to trigger DNA damage response/aneuploidy and G2/M arrest, respectively, MLN4924-induced radiosensitization in breast cancer cells appeared not to involve CDT1 or WEE1." (PMID 22457814, 2012). "While the RAD51 inhibitors synergized with WEE1 inhibition, no apparent synergistic effect was observed when combined with ATRi or DNA-PKi in MDA-MB-436 breast cancer cells." (PMID 35646698, 2022). "The expression of PKMYT1, but not of WEE1 and WEE1B, was significantly elevated in several solid tumours, especially in breast cancer and colorectal cancer." (PMID 31837068, 2020).
melanoma (104 papers, 2005 to 2026). A malignant, usually aggressive tumor composed of atypical, neoplastic melanocytes. "High expression of Wee1 has been associated with poor survival and higher recurrence rate in melanoma, ovarian carcinoma, gastric cancer and glioblastoma." (PMID 33320980, 2021). "High Wee1 expression is associated with poor prognosis in pediatric high-grade gliomas, malignant melanoma, and colorectal cancer." (PMID 31015476, 2019). "Our previous study with melanomas showed a similar association between high Wee1 protein expression and markers of malignancy, as found in vulvar carcinomas." (PMID 23767999, 2013). "Together these results suggest that high Wee1 protein expression is associated with increased proliferation in human melanomas." (PMID 22719872, 2012). "In conclusion, our results indicate that despite being an inhibitor of cell cycle progression, high expression of Wee1 is associated with malignancy and poor prognosis in patients with melanoma." (PMID 22719872, 2012). "Furthermore, WEE1 expression was closely associated with tumor-free survival rate, tumor burden, and the incidence of ulcer in melanoma, while WEE1 repression significantly reduced melanoma metastasis." (PMID 38231277, 2024). "Similarly, WEE1 expression was significantly associated with high tumor stage (p = 0.001), ulceration (p = 0.005), and poor disease-free survival (p = 0.008) in 108 melanoma patients." (PMID 33224881, 2020). "Cell cycle regulatory kinase Wee1 is upregulated in melanoma and is associated with poor prognosis." (PMID 24743024, 2014). "In contrast, in non-small-cell lung cancer and malignant melanoma, WEE1 is more highly expressed in low-grade lesions than in high-grade lesions, and the deletion of WEE1 has been reported to be an indicator of poor prognosis." (PMID 39335109, 2024). "WEE1 overexpression has been reported in various cancer types, including malignant melanoma, breast cancer, ovarian cancer, and glioma." (PMID 39335109, 2024). "The small molecule inhibitor adavosertib, targeting WEE1, has demonstrated cytotoxic effects alone and in combination with other treatments in melanoma, highlighting its potential for clinical application." (PMID 38474231, 2024). "Targeting WEE1 has been shown to increase DNA damage and cell death in melanoma cell lines, suggesting its potential as a therapeutic target." (PMID 38474231, 2024). "WEE1 is upregulated in melanoma compared to benign nevi and high WEE1 expression indeed correlated with a poor prognosis in melanoma patients." (PMID 35563772, 2022). "The combined inhibition of AKT3 and WEE1 kinases synergistically inhibited cellular proliferation and induced apoptosis in melanoma cells." (PMID 35563772, 2022). "Similar to the CHK1 inhibitors, WEE1 inhibitors were also primarily shown to abrogate the G2-M checkpoint in many tumor types, including melanoma." (PMID 35563772, 2022). "The synergistic effect of the combined CHK1 inhibitors with the WEE1 inhibitor adavosertib has been demonstrated in malignant melanoma." (PMID 35563772, 2022). "The inhibition of WEE1 by either overexpression of miR-155 or siRNA results in a significant decrease in metastasis in a mouse model of melanoma." (PMID 35563772, 2022). "Wee1 has been reported to be highly expressed in numerous malignancies including breast, hepatocellular, lung, melanoma, and others." (PMID 33320833, 2021). "Overexpression of Wee1 has also been observed in numerous malignancies, including breast and melanoma." (PMID 33320833, 2021). "Synergy has been achieved using Chk1 and Wee1 inhibitors together in melanoma, lymphoma, leukemia and other solid tumors." (PMID 33320980, 2021). "They demonstrated that miR-195 has an inhibitory activity on Wee1 expression in melanoma metastases." (PMID 34639030, 2021).
melanoma (continued). "In melanoma cells, Wee1 overexpression showed a strong, positive correlation with markers of proliferation: cyclin A, Ki67 and cyclin D3." (PMID 34639030, 2021). "Increased WEE1 mRNA expression has been observed in numerous solid tumor entities including hepatocellular carcinoma and melanoma." (PMID 33224881, 2020). "In the late stages of melanoma, during the metastasis process, decreased miR-155 and increased expression of WEE1 significantly contributed to the metastatic potential of melanoma cells." (PMID 32185171, 2020). "The combined inhibition of Wee1 and Chk1/2 has shown very promising effects when applied to other cancer cells but also melanoma cells." (PMID 30728057, 2019). "The Wee1 pathway has been explored in several types of cancer, such as kidney cancer, colorectal cancer, melanoma, and osteosarcoma." (PMID 31015476, 2019). "Consistently, GBMs and primary melanoma tumors that display elevated WEE1 mRNA expression exhibit significant down regulation of the IDH2 gene transcription." (PMID 29290954, 2017). "There were 10 such patients (patient #9, 11, 12, 15, 16, 17, 18, 19, 20 and 21) that fit in this category, indicating that about 71% (10 of 14) of the melanoma patients exhibit elevated WEE1/pY37-H2B signaling (90% CI: 0.128–0.432)." (PMID 29290954, 2017). "Further, increased WEE1 expression in glioblastomas and melanomas positively correlated with decreased IDH2 expression levels." (PMID 29290954, 2017). "Overexpression of WEE1 has been reported in several cancers, such as malignant melanoma, breast cancer, osteosarcoma and glioma." (PMID 27363019, 2016). "Among of them, malignant melanoma and high-grade glioma patients with WEE1 high-expression showed to correlate with malignancy." (PMID 27363019, 2016). "Bhattacharya and collaborators, by analyzing the expression levels of Wee1 in a series of melanoma patient samples and melanoma cell lines, found an inverse correlation between the expression of Wee1 and miR-195." (PMID 26694467, 2015). "MiR-195 regulation of Wee1 expression in malignant melanoma overcame cell cycle arrest upon stress conditions and an unrestricted growth of tumor cells." (PMID 26694467, 2015). "The WEE-1 inhibitor PD0166285 abrogates G2/M checkpoint inducing early cell division in the B16 melanoma cell line and this effect is related to microtubule stabilization and decrease in cyclin D transcription." (PMID 25914884, 2015). "Together these results reveal the importance of Wee1 as a prognostic biomarker in melanomas, and indicate a potential role for targeted therapy, alone or in combination with other agents." (PMID 22719872, 2012). "It is therefore likely that the high levels of Wee1 observed protect the melanoma cells against DNA damage and cell death." (PMID 22719872, 2012). "Together our results indicate a role of Wee1 in proliferation and genomic stability in malignant melanoma, thus potentially making the kinase an eligible therapeutic target." (PMID 22719872, 2012). "We studied the mechanisms by which the Wee1 inhibitor PD0166285 suppressed growth of the B16 mouse melanoma cell line." (PMID 17177986, 2006). "We analyzed the effect of Wee1 inhibitor PD0166285 described first by Wang in the G2 transition in the B16 melanoma cell line." (PMID 17177986, 2006). "In addition, WEE1 expression has been reported to correlate with the prognosis of malignant melanoma and high-grade gliomas." (PMID 39335109, 2024).
melanoma (continued). "In the context of cancer, WEE1′s role in cell cycle regulation has been shown to promote cell survival in various types of malignancies, including breast cancer, leukemia, melanoma, brain tumors, and CRC." (PMID 39273409, 2024). "However, the role of WEE1 expression in melanoma progression and aggressiveness is somehow controversial." (PMID 35563772, 2022). "Adavosertib (previously named AZD-1775) is a pyrazolo-pyrimidine derivative, acting as an ATP competitive potent and selective small molecule inhibitor of WEE1, and displays cytotoxic activity as a single agent in many cancer cell lines, including melanoma cells." (PMID 35563772, 2022). "Transfections using siWEE1 in metastatic melanoma cell lines (WM239, WM45.1, LOX) further support the hypothesis of a potential tumor-promoting role of WEE1 in melanoma." (PMID 33224881, 2020). "We could clearly show that combined inhibition of Chk1/2 and Wee1 synergistically killed BRAFi-resistant cells and more importantly, reduced tumor growth by up to 50% in an in vivo melanoma mouse model." (PMID 30728057, 2019). "The combination of Wee1 and Chk inhibitors both targeting key enzymes of cell cycle control can kill melanoma cells independent of their BRAF mutation status." (PMID 30728057, 2019). "Future development of WEE1 ‛epigenetic inhibitor’ could facilitate specific targeting of many of WT BRAF melanomas, GBMs, triple negative breast cancers (TNBCs) and castration resistant prostate (CRPCs), which currently have a few therapeutic options." (PMID 29290954, 2017). "Given the high prevalence of WT BRAF in melanomas, we reasoned that melanomas with wild-type BRAF may exhibit a dependence on WEE1 epigenetic pathway activation for maintenance of the transformed phenotype." (PMID 29290954, 2017). "Overall, our data reveal a novel mode of WEE1 mediated IDH2 downregulation as a recurrent epigenetic alteration that may be operational in melanomas, GBMs and prostate cancers." (PMID 29290954, 2017). "Not only is WEE1 overexpressed in melanomas, AZD1775, a potent WEE1-specific inhibitor selectively induces apoptosis in WEE1 expressing cancer cell lines, suggesting that some of the melanomas may be utilizing the WEE1 signaling pathway for survival." (PMID 29290954, 2017). "High expression of WEE-1 in malignant melanoma correlates with poor disease-free survival." (PMID 25914884, 2015). "This reduction in Wee1 levels was seen in both HeLa cells and in A375 melanoma cells." (PMID 24424027, 2014). "As opposed to this, targeting of Wee1 has in itself been sufficient to cause apoptosis and alterations in cell cycle distribution in other cancer cell lines, including melanoma." (PMID 23767999, 2013). "Based on these findings, we hypothesize that Wee1 contributes to increased proliferation in melanomas." (PMID 22719872, 2012). "To assess the role of Wee1 in development and progression of malignant melanoma we examined its expression in a panel of paraffin-embedded patient derived tissue of benign nevi and primary- and metastatic melanomas, as well as in agarose-embedded cultured melanocytes." (PMID 22719872, 2012). "In the present study, we demonstrate for the first time that Wee1 is up-regulated in human malignant melanomas as compared to normal melanocytes and benign nevi, and that high expression of Wee1 is associated with poor disease-free survival and markers of increased tumor cell proliferation." (PMID 22719872, 2012). "Taken together, these data indicate that WEE1 epigenetic inhibitor could have a significant impact on treatment of melanomas lacking V600 mutation, a critical unmet clinical need." (PMID 29290954, 2017).